BCL2 (BCL2 apoptosis regulator)
Diseases named in the same sentence as BCL2 in open-access papers (continued):
Sharing a sentence is not in itself a finding about the gene and the disease.
cancer (continued). "The PC cases were categorized using T staging in order to assess the association between serum levels of NEAT1, miR-129-5p, and their related targets BCL2 and TGF-β1 with cancer progression." (PMID 40730640, 2025). "These ongoing efforts underscore the critical need to develop effective Bcl-2-targeted strategies to improve outcomes for HCC patients, particularly given the challenges of drug resistance in this aggressive cancer." (PMID 40841912, 2025). "Taken together, these data highlight that the anti-apoptotic BCL2 proteins BCL2, BCL-XL, and MCL1 are all highly promising therapeutic targets in multiple cancer types." (PMID 40113751, 2025). "The downstream targets of STAT3 include anti-apoptotic genes (BCL-2, BCL-XL, MCL-1), cell survival pathway genes (Cyclin-D1, Survivin), drug efflux (MDR1), and maintenance genes of cancer stem cells (CD133)." (PMID 40149331, 2025). "ALDHs govern drug resistance, activation of BCL2, AKT, drug efflux pumps and differentiation in cancer stem cells." (PMID 40179083, 2025). "miR-34a mediates cell signaling pathways dependent on cancer cell apoptosis including: EGFR, PDGFR-α/β, MET, SIRT1, NOTCH1, BCL2, and HMGB1." (PMID 40061926, 2025). "Bcl-2, an anti-apoptotic proto-oncogene, is highly expression in NSCLC (37% of cases) and plays a role in cancer cell apoptosis." (PMID 39859343, 2025). "The viability of cancer cells and lung CAFs post-treatment with ABT-199, a Bcl-2 inhibitor, was evaluated using MTT assays." (PMID 40575163, 2025). "Modification of cancer biomarkers, such as decreased PCNA and Ki-67, increased Bax/Bcl-2 ratio, increased cleaved caspase-3, decreased VEGF and CD31, and decreased matrix metalloproteinases, especially MMP-2 and MMP-9, were also observed." (PMID 41322296, 2025). "These small molecules antagonize anti-apoptotic proteins such as BCL-2, MCL-1, or BCL-XL, on which cancer cells depend for their survival." (PMID 40365276, 2025). "Our study identified core genes (ALB, BCL2, EGFR, IL-6, and STAT3) enriched in cancer pathways, suggesting a potential link between cancer-related metabolic dysregulation and fatigue." (PMID 40435272, 2025). "For example, responsible genes in the regulation of cancer cell survival and proliferation such as STAT1, STAT5A, CD44 and BCL2 are upregulated." (PMID 39056676, 2024). "In the development and progression of cancer, AKT1, JUN, IL6, SRC, EGFR and BCL2 plays a critical role." (PMID 39011503, 2024). "Our data analysis identified ERBB2 as a direct regulator of key oncogenes such as MYC and BCL2, and tumor suppressors like PTEN in several cancers including PC." (PMID 39409883, 2024). "The high expression of PKP1 facilitated cancer cells to form clusters in circulation and also activated the PI3K/AKT/Bcl–2–mediated pathway to increase cell survival." (PMID 38595789, 2024). "A gold nanoparticle (AuNP)-based delivery system to co-deliver Bcl-2 siRNA and doxorubicin (DOX) for more effective cancer therapy was developed by C. Ü." (PMID 39274842, 2024). "It suppresses miR‐32 expression, downregulates BCL‐2 expression, upregulates BAX, Bim, and cytosolic CytC expression, promotes cleavage of caspase‐3 and ‐9 proteins, halts the cancer proliferation, and stimulates apoptosis." (PMID 38726411, 2024). "It has been noted that the ERK1/2 pathway can regulate BCL-2 protein activity to promote cell survival, and inhibiting ERK1/2 signaling, either directly or indirectly, can induce cancer cell death." (PMID 38732133, 2024). "We also investigated the dependency profile of BCL2 family proteins (BCL2, BCL2L10, BCL2A1, BCL2L1, and MCL1) in GBM within Cancer Cell Line Encyclopedia, and found that GBM cells show the greatest dependency on Bcl-xL (BCL2L1) for survival." (PMID 38383492, 2024).
cancer (continued). "CCND1 (Cyclin D1), MPP2 (Membrane palmitoylated protein 2), Bax, Bcl2, HIF1A and VEGFA are transcriptionally regulated molecules that are related to cell proliferation, apoptosis and cancer cell invasion and metastasis processes." (PMID 39834948, 2024). "These compounds target key oncogenic pathways, such as those regulated by Bcl-2, HER2, p120, MMP-2, and MMP-9—proteins essential for cancer cell survival and metastasis." (PMID 39840104, 2024). "Research shows that the balance between anti-apoptotic and pro-apoptotic proteins, such as BCL2 and BAX, works well for the proliferation of cancer cells." (PMID 39605919, 2024). "Another approach is to target hyperactivated oncogenic pathways that regulate the expression or activity of anti-apoptotic BCL2 proteins (e.g., MAPK or PI3K pathways), thereby specifically targeting cancer cells." (PMID 39286979, 2024). "BECLIN-1, through the interaction with BCL-2 protein, also promotes the release of pro-apoptotic molecules, like BAX and BAK in some type of cancer cells." (PMID 39555455, 2024). "BCL2 is a known target of IL4 signaling and an important regulator of apoptosis that has become a target of interest in several cancers." (PMID 38731867, 2024). "The expressions of Bcl-2, IL-6, AKT, and P38 were significantly increased in the cancer tissues than in normal tissues while Bax level was significantly increased in non-cancerous tissue than in cancer tissue." (PMID 38072891, 2024). "In A549 lung cancer cells, quinoa extracts at a concentration of 1.92 mg/mL demonstrated potent anti-cancer activity by upregulating BAX and downregulating Bcl2 levels to promote apoptosis." (PMID 39061898, 2024). "Recently, Venetoclax, a BCL-2 inhibitor, has been utilized in clinical for treating AML, targeting BCL-2 proteins to induce apoptosis in cancer cells." (PMID 38643300, 2024). "So, downregulation of STAT3-regulated gene expression (Bcl-2, survivin, and VEGF) inhibits cancer cell proliferation and induces apoptosis." (PMID 38310190, 2024). "Current forms of chronic cancer therapy involve the use of BH3-mimetic drugs, which are designed to activate apoptosis by inhibiting anti-apoptotic BCL-2 group proteins." (PMID 39338354, 2024). "The development of cancer mostly relies on the misbalance between pro-apoptotic proteins (e.g., BAX) and anti-apoptotic proteins (e.g., BCL2)." (PMID 39062071, 2024). "Since cancer resistance to the BCL2 inhibitor venetoclax is based on the upregulation of alternative anti-apoptotic factors such as MCL1, the suppression of both BCL2 and MCL1 by 3a appears especially promising." (PMID 39062194, 2024). "CG methylation has been reported to induce conformational changes of iMs from CpG islands of four genes related to cancer (VEGF, C-KIT, BCL2 and HRAS)." (PMID 38180820, 2024). "In our study, upon treatment with LP 1010 CFU/mL the protein level of Bcl-2 was decreased, whereas BAX levels were increased in all three cancer cell lines, thus revealing one molecular mechanism for the apoptosis of the tested cancer cells." (PMID 38258008, 2024).
cancer (continued). "PI3K and MAPK proteins as well as RAC1 BCL2 and PPIA were found to be overexpressed between cancer tissues and healthy controls." (PMID 39409902, 2024). "BH3 mimetics represent such a class of the anti-cancer drugs, which essentially mimic the action of BH3-only proteins and antagonize the inhibitory effects of anti-apoptotic Bcl-2 proteins." (PMID 40150937, 2024). "Mechanistically, RVS downregulates the ATF4/Chop/BCL-2/BAX signaling pathway, contributing to anti-aging and anti-cancer effects and synergistic effects with agents like prednisolone enhance apoptosis through BAX and BCL-2 modulation." (PMID 39769099, 2024). "Ligand binding to TAM family receptors activates downstream signaling pathways critical for cancer, including the JAK-STAT, MAPK-ERK, and PI3K-AKT-mTOR pathways and pro-survival pathways involving BCL-2 and SURVIVIN." (PMID 39199601, 2024). "Western blot analysis revealed a marked increase in BAX and PARP1 expression in cancer cells treated with anlotinib alone or in combination with DDP, accompanied by a decrease in BCL2 expression." (PMID 39508048, 2024). "Previous preclinical studies have shown that BTK inhibition enhances mitochondrial BCL-2 dependence, thereby enhancing the ability of a BCL-2 inhibitor to kill cancer cells." (PMID 39060763, 2024). "The high doses of Mocetinostat drug significantly induce apoptosis and suppress cancer cell proliferation through increased pro-apoptotic proteins (BAX) and a down level of anti-apoptotic proteins(Bid, Bcl2)." (PMID 38645087, 2024). "In vitro analyses revealed significant anti-cancer effects of SPGE extract in MCF‐7 and MDA-MB-231 cell lines (cytotoxicity, caspase‐3/-7, Bcl‐2, Annexin V/PI, cell cycle, BrdU, and mitochondrial membrane potential)." (PMID 38464730, 2024). "As NF-κB binding sites have been identified in the promoters of Bcl-2, Bcl-xL, and survivin, it is suggested that genistein may inhibit their expression through NF-κB downregulation, thereby sensitizing cancer cells to apoptosis induced by docetaxel, cisplatin, or doxorubicin." (PMID 39519572, 2024). "Immunofluorescence analysis corroborated these findings, demonstrating a significantly increase in BAX fluorescence intensity in cancer cells treated with anlotinib alone or in combination with DDP, while the fluorescence intensity of BCL2 was decreased." (PMID 39508048, 2024). "Baicalin has also been reported to reduce the levels of ILs, Bcl2, and VEGF, showing cancer-preventive effects." (PMID 39246660, 2024). "Drugs targeting AURKB, BCL-2, or EZH2 are currently in various stages of clinical development and have shown promising results for treating certain cancers." (PMID 38961535, 2024). "ABT-737 neutralizes anti-apoptotic BCL-2 and BCL-XL, triggering the release of cytochrome c and caspase activation especially in cancer cells." (PMID 38977850, 2024). "It specifically targets BCL-2, BCL-xL, and BCL-w proteins, releasing pro-apoptotic proteins, thus inducing programmed cell death in cancer cells." (PMID 38643300, 2024). "Bcl2 is known to suppress cancer cell apoptosis, and our further evidence for the oncogenic role of LINC01405 comes from Bcl2 upregulation following LINC01405 overexpression in the cell lines of SKBR3." (PMID 38225865, 2024).
cancer (continued). "These marker genes play diverse roles in cancer, such as promoting growth and proliferation (MYC, HIF1A, ATM), inhibiting apoptosis (MCL1, BIRC3, BCL2) and facilitating invasion (CXCR4, CD55)." (PMID 38982317, 2024). "The abnormal overexpression of MCL1, BCL2, and related antiapoptotic BH3 family genes helps to stabilize mitochondria, promoting tumorigenesis and drug resistance in various cancers." (PMID 39590121, 2024). "Anti-apoptosis factors including MCL1, BCL2, BCLxL and BFL1 are crucial mediators of tumorigenesis and resistance to therapy in various cancers." (PMID 38371625, 2024). "It has become clear that MCL-1 has a binding profile different from BCL-2/BCL-XL/BCL-w, and neutralising MCL-1 kills many cancer cells efficiently." (PMID 39285161, 2024). "When paired with Palmarosa sempervirens or radix trichosanthis, APS induces apoptosis in cancer cells, such as B16F10 and A375 melanoma cells, by suppressing PI3K, Akt, and Bcl-2 mRNA expression levels." (PMID 38794206, 2024). "K-means clustering of >600 000 cancer cells and cell level intensities of APAF1, procaspase-9, procaspase-3, XIAP, SMAC, BAX, BAK, BCL2, BCL-XL, MCL-1, procaspase-8, BID, FADD, FLIP, RIP3 and CIAP1 identified distinct cell cluster profiles." (PMID 39886119, 2024). "This conjugate contained multiple mucin-1 aptamers and Bcl2-specific siRNA, which were attempted to transfect into mucin-1 overexpressing MCF-7 breast cancer cells for combination cancer therapy." (PMID 36778126, 2023). "Among the five antiapoptotic genes, three (BCL2, BCL2A1, and MCL1) can be regulated by NF-κB in different types of cancer cells." (PMID 36853387, 2023). "Meanwhile, numerous target genes of miR-34c-5p have been identified in cancers, such as E2F3, BCL-2, and c-Met." (PMID 37670265, 2023). "Following 72 h of TC-1 cancer cell lines treated with the RSV-A2 at the MOIs ranging from 1 to 15, the apoptotic gene expressions of Bax and Bcl2 were analyzed by Real-time PCR." (PMID 37641004, 2023). "Solanine treatment is further characterized by increased Bax expression, decreased Bcl-2 levels, and diminished platelet–endothelial cell adhesion molecule (CD31) expression in cancer cells." (PMID 38192621, 2023). "Both types of juices were able to inactivate the BCL-2 protein in MCF-7 and MDA-MB-231 cancer cell lines." (PMID 37108053, 2023). "These 1,670 genes involved well-established cancer-related genes, including MYC, MYB, BRCA2, ERCC4, and MET for s1 subtype and TERT, BCL2, and SUZ12 for s3 subtype." (PMID 36731467, 2023). "The secreted FGF2 promotes survival of neighboring cells through MEK/ERK‐induced upregulation of BCL2 or MCL1 and leads to anti‐cancer drug resistance." (PMID 37553811, 2023). "The siRNA targeting the apoptosis inhibitor protein Bcl-2 was covered by a layer of PEG-Poly (acrylic acid)-folic acid to prolong circulation and enhance cancer cell targeting." (PMID 37275244, 2023). "Thousands of mRNAs are ELAVL1 targets, including factors fostering diverse cancer traits such as proliferation (cyclins A2, B1, D1, and E1), angiogenesis (HIF1a, PTGS2, and VEGFA), survival (BCL2 and MCL1), and invasion (MMP9 and SNAI1)." (PMID 37298909, 2023).
cancer (continued). "The BCL-2-selective inhibitor ABT-199 (Venetoclax) is a potent and orally bioavailable anti-cancer drug in several cancer cells, including TNBC cells." (PMID 37242775, 2023). "DNS treatment upregulated Bcl-2 expression while downregulating Bax, MMP-2, MMP-9, mTOR, and Akt levels in cancer cells." (PMID 38192621, 2023). "We also discuss therapeutic strategies to target these regulators of apoptosis for cancer therapy, for example using BH3-mimetic drugs which inhibit selective pro-survival BCL-2 proteins." (PMID 36342579, 2023). "These molecules are critical for maintaining cell survival (Akt and Bcl-2) and promoting cell apoptosis (JNK and p38) in the oxidative stress of cancer cells." (PMID 38027228, 2023). "So, downregulation of TGFB2 results in the expression of anti-apoptotic proteins BCL2 and BCL-W, and enhanced cancer cell survival, which confers platinum resistance in NSCLC and 5-FU resistance in CRC cells, respectively." (PMID 37239828, 2023). "Melatonin regulated the protein expressions of the HIF-1α and Bcl2 pathways’ downstream proteins, including MCL1, Bcl-XL, Bax, claspin, and survivin, which possess anti-cancer effects in numerous cancer cell types." (PMID 37086261, 2023). "NFκB confers anoikis resistance because NFκB targets genes like CIAP2, survivin, BCL2, BCLxl, and XIAP, which make cancer cells resistant to anoikis." (PMID 37308913, 2023). "BCL2 contributes to the release and infiltration of CCL2 protein, which accelerates cancer progression and correlates with high PSA." (PMID 36329628, 2023). "Among them, ACVRL1 is associated with the TGF-β pathway, which hampers antitumor immune response; Bcl-2 regulates the apoptosis pathway, which correlated inversely with TMB in four cancer types." (PMID 36911742, 2023). "ICRN and icaritin increase cytochrome c secretion, Bax/Bcl2 ratio, poly (ADP-ribose) polymerase and caspase stimulation in various types of cancer cells." (PMID 36662090, 2023). "BCL2 is an important regulator of apoptosis, and BH3 mimetics are known to be cytotoxic and are even in clinical use to target cancer cells." (PMID 37759469, 2023). "The anti-apoptotic BCL-2 proteins can be counterbalanced by proapoptotic BH3-only BCL-2 proteins; as such, the BH-3 mimetics were developed to promote apoptosis in cancer cells." (PMID 39872303, 2023). "Steroidal saponins showed anti-cancer activities on several tumor cells via different mechanisms, including downregulating MAPKs, PI3K/Akt/mTOR, MEK/ERK1/2, and Bcl-2." (PMID 36984763, 2023). "We confirmed the presence of apoptosis in cancer cells by assessing apoptosis-related protein markers, including PARP, the anti-apoptotic protein Bcl-2, and the pro-apoptotic protein Bax, using Western blot analysis." (PMID 38132948, 2023). "In cancer cells, ICRN significantly reduces the expression of microRNA 21 and the Bcl-2 protein, and increases the expression of PTEN and RECK protein." (PMID 36662090, 2023). "Mechanistic studies have shown the modulation of apoptosis related proteins such as BCL-2 and BAX with varying expression of IL-8 suggesting the involvement of Hsp60-IL-8 axis in apoptosis resistance in cancer." (PMID 37232720, 2023).